CD200 (CD200 molecule)
Diseases named in the same sentence as CD200 in open-access papers (continued):
Sharing a sentence is not in itself a finding about the gene and the disease.
melanoma (continued). "Expression of CD200 in human cell lines derived from melanomas is strongly correlated with transcripts including MITF, endothelin receptor type B and silver homolog." (PMID 33562512, 2021). "In this study, we used the human-relevant, CD200 expressing Yumm1.7 tumor model to evaluate the role of CD200-CD200R pathway in melanoma tumor growth, immunity and immunotherapy." (PMID 34692697, 2021). "Given that CD200R-deficiency or anti-CD200 treatment leads to reduced T cell responses in TME, using blockade of CD200 as an immunotherapy for cancers such as melanoma should be practiced with caution." (PMID 34692697, 2021). "CD200 blockade is considered a strategy for immunotherapy of CD200-positive cancers such as melanoma." (PMID 34692697, 2021). "The dependence of ERK for expression of CD200 helps explain the low levels seen in normal melanocytes and melanoma cell lines where p-ERK is low, and the high levels in cell lines with high expression of p-ERK." (PMID 33562512, 2021). "The high expression levels of CD200 on human melanomas are again correlated with decreased levels of CTL and a shift from a Th1 to a Th2 cytokine profile, with marked inhibition of IFN-γ." (PMID 33562512, 2021). "In humans, certain tumor cell types including melanoma cells, ovarian cancer cells, malignant B cells and cells from some neuroendocrine neoplasms overexpress CD200." (PMID 32656079, 2020). "Our group has recently confirmed that almost the 70% of MM cells in BM specimens express CD200 and, as in melanoma, the dependence of CD200 expression on RAS/RAF/MEK/ERK pathway." (PMID 25013764, 2014). "In mixed lymphocyte reactions with T cells, DCs, and melanoma cells, T cells produced larger amounts of IL-2 when CD200 in melanoma cells was knocked down with shRNA specifically targeting the CD200 ligand." (PMID 24194739, 2013). "To investigate the role of cancer cell expression of CD200 in tumor formation and metastasis, we generated CD200-positive and CD200-negative B16 melanoma cells." (PMID 22319630, 2012). "Recent studies have revealed that CD200 is also expressed in a variety of human cancer cells including human melanoma, ovarian cancer, myeloid leukemia cells and malignant B cells." (PMID 22319630, 2012). "Subcutaneous injection of CD200-positive B16 melanoma cells inhibited tumor formation and growth in C57BL/6 mice but not in Rag1−/−C57BL6 mice." (PMID 22319630, 2012). "In contrast, the lungs from mice injected with B16.OVA.CD200 cells had much less melanoma foci, and the differences were highly significant in terms of total foci numbers and total lung weight." (PMID 22319630, 2012). "The lungs from mice who received B16.OVA.CD200 cells had much less melanoma foci compared with the lungs from mice that received B16.OVA.Ctrl cells." (PMID 22319630, 2012). "In this study we found that adoptive transfer of antigen-specific T cells (both CD4 and CD8) also significantly promoted survival of mice with CD200-positive melanoma tumors over CD200-negative tumors." (PMID 22319630, 2012). "In our current study, we have clearly shown that depletion of a large population of CD200R+ myeloid cells (Ly6G+) using anti-Gr1 mAb achieved a similar effect to CD200 expression on melanoma cells." (PMID 22319630, 2012). "This correlated with profound inhibition of tumor formation and metastasis of CD200+ B16 melanoma in the lung while the effect was diminished in the periphery." (PMID 22319630, 2012). "CD200 has also been shown to have a protective effect in melanoma and non-small cell lung cancer." (PMID 40718780, 2025). "However, there have been studies in a melanoma model that have shown that CD200 expression in melanoma has an anti-tumor effect." (PMID 38619621, 2024). "In addition, a separate melanoma study concluded that tumoral expression of CD200 similarly alters the tumor microenvironment by inhibiting IL-10 production from TAMCs." (PMID 38137547, 2023).
melanoma (continued). "In addition, when coupled with adoptively transferred CTL therapy, this study reported that CD200 expression in melanoma cells permitted better infiltration of activated and tumor specific CTLs." (PMID 38137547, 2023). "In this respect, by inhibiting IL-10 production, CD200 tumoral expression may serve a favorable role in melanoma by facilitating the transition of TAMCs to the M1 phenotype." (PMID 38137547, 2023). "In studies using neuroblastoma and melanoma murine models, the absence of CD200/CD200R signaling (using CD200R- mice) caused TAMCs to upregulate CCL24 and CCL8 levels but downregulate the production of CXCL3, CXCL2, and CCL3." (PMID 38137547, 2023). "In this work, we investigated whether CD200 blockade could be used as a potential therapy in melanoma." (PMID 34692697, 2021). "In this study, we evaluated these issues using the CD200+ Yumm1.7 mouse melanoma model." (PMID 34692697, 2021). "To determine if CD200 blockade could inhibit the growth of CD200+ melanoma, we tested a monoclonal antibody (OX-90) in the Yumm1.7 tumor model." (PMID 34692697, 2021). "Moreover, MEK inhibition with U0126 and knockdown of mutant BRAF resulted in reduced expression of CD200 mRNA in melanoma cell lines." (PMID 24194739, 2013). "However, expression of CD200 on melanoma cells dramatically affected tumor foci formation in the lungs." (PMID 22319630, 2012). "As we showed in other tumor models, we further confirm here that CD200-positive melanoma tumors are more susceptible to antigen specific T cell therapy compared to CD200-negative melanoma." (PMID 22319630, 2012). "Recent studies have revealed that CD200 is frequently expressed on human melanoma cells." (PMID 22319630, 2012). "However, i.v. injection of CD200-positive B16 melanoma cells dramatically inhibited tumor foci formation in the lungs of both C57BL/6 and Rag1−/−C57BL6 mice." (PMID 22319630, 2012). "To test the significance of melanoma expressed CD200 in tumor formation and metastasis, we generated CD200-positive and CD200-negative B16 melanoma cells by transfecting the B16.OVA cells with either the empty pCDNA3 expression vector or one carrying the murine CD200 cDNA." (PMID 22319630, 2012). "To test if expression of CD200 on melanoma cells could improve the susceptibility to T cell therapy, we injected 5×105 of B16.OVA.Ctrl or B16.OVA.CD200 tumor cells into each Rag−/−C57BL/6 mouse subcutaneously." (PMID 22319630, 2012). "In fact, the expression of the cognate ligand of CD200, CD200R, is restricted to certain populations of T cells and mainly to myeloid-derived Ag presenting cells, among which tumor-associated myeloid cells whose suppression, that is, in melanoma model, is able to abrogate tumor formation." (PMID 25013764, 2014). "Thus, expression of CD200 on melanoma cells improves the efficacy of T cell therapy." (PMID 22319630, 2012). "As demonstrated in melanoma studies, TAMC levels were inversely proportional to CD200 expression, suggesting that CD200/CD200R signaling suppresses the expansion of TAMCs." (PMID 38137547, 2023). "Given that CD200R-deficiency or anti-CD200 treatment leads to reduced T cell responses and fails to show benefits either alone or in combination with checkpoint inhibitors, blockade of CD200 should not be considered for immunotherapy of cancers such as melanoma." (PMID 34692697, 2021). "The CD200/CD200R signaling pathway is a key regulator of immune responses, known for its immunosuppressive effects in various physiological and pathological contexts, including malignancies such as melanoma." (PMID 40075669, 2025). "Overall, our results show that the growth of CD200+ Yumm1.7 melanoma is enhanced when CD200R signaling is absent." (PMID 34692697, 2021). "A study on mice with CD200-negative melanoma tumors showed that treatment with an agonistic anti-CD200R mAb inhibited the tumor formation and metastasis in the lungs of the animals, via inhibition of myeloid cell functions." (PMID 32656079, 2020).
melanoma (continued). "Expression of CD200 on melanoma cells did not significantly affect subcutaneous tumor formation and growth, and it also did not significantly affect the survival of tumor bearing mice." (PMID 22319630, 2012). "To test this hypothesis, we tested the efficacy of an agonistic anti-CD200R mAb (OX110) in the treatment of lung metastasis of CD200-negative melanoma." (PMID 22319630, 2012). "To test this hypothesis, we have generated CD200-positive and CD200-negative B16.F10.OVA melanoma cells." (PMID 22319630, 2012). "Thus, the production of CCL24 and CCL8, and the reduction of CXCL3, CXCL2, and CCL3 in TAMCs, explain why mice lacking intact CD200/CD200R signaling more potently rejected neuroblastoma and melanoma tumors relative to wild-type conditions." (PMID 38137547, 2023).
multiple myeloma (25 papers, 2016 to 2025). "The over-expression of CD200 is linked with expansion of suppressive Treg cells and plays a vital role in the progression of multiple myeloma." (PMID 32856848, 2020). "Besides, in a recent study, CD200 expression in plasma cell myeloma (PCM) was found to be associated with lower β2-microglobulin." (PMID 26910908, 2016). "Several studies have correlated high levels of CD200 expression in myeloma cells with worse prognostic." (PMID 38455039, 2024). "In our study, we observed that the rate of MYXV increased in myeloma cells from patients with refractory MM after CD200 blockade." (PMID 38251379, 2024). "Studies have reported that CD200 is expressed in haematological malignancies such as multiple myeloma (MM), acute myeloid leukaemia (AML) and acute lymphoblastic leukaemia (ALL)." (PMID 37822353, 2023). "CD200 expression was found up-regulated in several mature hematopoietic-related cancers with a potential prognostic impact such as in multiple myeloma." (PMID 33028033, 2020). "The expression of CD200+ positively correlates with the percentage of Treg in multiple myeloma patients." (PMID 32212802, 2020). "CD200 is expressed on a wide range of tumors, including lymphomas, myelomas, leukemias, and gliomas, and CD200 expression is correlated with expression of epithelial cancer stem cell markers on prostate, brain, breast, and colon cancers." (PMID 28515726, 2017). "CD200 is expressed on myeloma, plasma cells, and in most patients with CLL." (PMID 37760396, 2023). "Thus, patients with overexpression of CD200 on multiple myeloma cells (MMc), despite high-dose chemotherapy and ASCT, are reported to have a shorter event free-survival (EFS) compared to patients whose MMc do not overexpress CD200." (PMID 33562512, 2021). "Both studies were terminated, but the second one published results showing that administration of the drug was associated with reduced expression of CD200 on B-cells and CD4+ effector T-cells of B-CLL individuals, however inefficient in the three myeloma patients evaluated." (PMID 32656079, 2020). "CD200 expression as a prognostic factor has been studied in multiple myeloma (MM)." (PMID 26910908, 2016). "It has been reported that CD200, TMIGD2 and TNFSF14 can facilitate anti-tumor immune responses by enhancing T and NK cell activity in multiple myeloma and hematologic malignancies." (PMID 40342824, 2025). "Our panel incorporated antigens rarely included in myeloma MRD panels, like CD200 and CD28." (PMID 34485145, 2021). "In addition, an increase in CD200 (hsc and pre-BI), Nanog (hsc and pre-pro-B), sXBP-1 (pre-pro-B and pro-B), Oct3/4 (pre-BI), and CD81 (pre-BI) and a decrease in CD362 (hsc and pro-B) are noted only in MGUS or SMM, showing clonal hematopoiesis extending to premalignant stages of myeloma." (PMID 36752202, 2023). "CyIgκ and cyIgλ are extremely important to confirm the clonality of myeloma cells, and thus, ruling out the polyclonal cells, which express aberrant antigens such as CD56 and CD200, is impossible without anti-cyIgκ and anti-cyIgλ antibodies." (PMID 34045494, 2021). "Both CD200 and CD200R have been thoroughly studied in hematologic malignancies; CD200 is an independent negative prognostic factor for patients with chronic lymphocytic leukemia (CLL), acute myeloid leukemia (AML), multiple myeloma (MM) and myelodysplastic syndromes (MDS)." (PMID 33804482, 2021).
glioma (22 papers, 2012 to 2025). A benign or malignant brain and spinal cord tumor that arises from glial cells (astrocytes, oligodendrocytes, ependymal cells). "The downregulation of CD200 expression in CD200-rich glioma cells could foster the formation of an activated microglia-associated tumor microenvironment, leading to glioma progression." (PMID 34071306, 2021). "By binding to CD200 inhibitory receptors (CD200R) on the cell membranes of immune cells, glioma-secreted CD200 suppresses a normal immune response to the tumor." (PMID 39794971, 2024). "In a dog model of high-grade glioma, a synthetic peptide that targeted the immune checkpoint protein, CD200, enhanced the functional ability of antigen-presenting cells to activate T-cells for an anti-glioma response." (PMID 38540350, 2024). "Using parent rat C6 glioma cell lines, and cells transduced to express either CD200 or CD200tr, a comparison of growth in neonatal Wistar rat forebrain parenchyma was monitored (all lines equivalently grew in vitro)." (PMID 38540350, 2024). "This significant increase in post-surgery survival time for dogs receiving CD200AR-L was attributed to reduced CD200 expression on T cells and APCs and, therefore, their increased activities within the glioma TME." (PMID 36756156, 2023). "Another study investigated the effect of CD200 on tumor progression using a metastasis model in rats transplanted with glioma cells." (PMID 37894750, 2023). "The CD200 trial only evaluated high-grade glioma cases, which limits direct comparison with the current trial results." (PMID 36644324, 2022). "Administration of a synthetic peptide targeting the immune checkpoint protein, CD200, enhanced the capacity of antigen-presenting cells to prime T-cells to mediate an anti-glioma response." (PMID 30682795, 2019). "In this study, gliomas were treated with cytoreductive surgery followed by intradermal injection of a CD200-directed peptide prior to delivery of an autologous tumor lysate vaccine." (PMID 31788444, 2019). "In this study, we demonstrated that certain CD200 peptides enhance the efficacy of autologous tumor cell lysate therapeutic vaccines in pet dogs with high-grade glioma as evidenced by significantly increased survival times." (PMID 30682795, 2019). "Our data suggest that gliomas have co-opted CD200-mediated immune suppression to persist, and that blocking the CD200/CD200R immune checkpoint is a viable strategy for glioma therapy." (PMID 25598973, 2014). "To investigate the potential role of CD200 in GL261 glioma induced immune suppression, we incorporated the CD200R antagonist 6059 into our vaccine inoculum." (PMID 25598973, 2014). "Given its high expression on normal CNS tissue, we investigated the expression of CD200 on multiple central nervous system tumors." (PMID 25598973, 2014). "CD200 is an immune checkpoint glycoprotein that is highly expressed in glioma." (PMID 39794971, 2024). "Meanwhile, CD48 had also been studied and its high expression in gliomas might lead to a lower survival rate, while for CD200, its higher expression might prolong microglia activation and tumor growth." (PMID 39039366, 2024). "Wistar rats transplanted with C6 glioma cells expressing truncated CD200, which lacks the sequence for CD200R binding, revealed lung metastasis in 44% of the total individuals, whereas rats transplanted with C6 cells expressing full-length CD200 progressed to lung metastasis in all cases." (PMID 37894750, 2023). "Here we examine whether an inhibitor of the CD200 (OX2) immune checkpoint augments the efficacy of autologous tumor lysate vaccines against high-grade glioma, including glioblastoma." (PMID 30682795, 2019). "This suggests that CD200 is a central driver of glioma-mediated immune suppression." (PMID 25598973, 2014).
glioma (continued). "The results of our investigation showed a strong relationship between the expression of SMARCAL1 and several immune checkpoint genes, including CD276, NRP1, TNFSF4, CD40, CD200, and CD80 in Glioma, LUAD, LIHC, KIRC, and UCEC." (PMID 39994264, 2025). "Peptide inhibitors targeting CD200 have been shown to enhance immune function in TME by modulating cytokines and dendritic cells, resulting in the suppression of glioma." (PMID 39491527, 2024). "Here, it is possible that the glioma of boxers and Boston terriers responded to ATL and CD200 ICI, potentially mediated by treatment-mediated suppression of the mTOR-PI3K axis." (PMID 39794971, 2024). "The GSEA results here suggest that examining this potential relationship could reveal a mechanism by which some canine glioma respond to ATL and CD200 ICI." (PMID 39794971, 2024). "A study investigating high-grade glioma in mice found that administering CD200AR-L in addition to tumor-derived vaccines improved the animals’ immune response, which was originally diminished due to CD200 expression on cancer cells." (PMID 36756156, 2023). "Moreover, a separate glioma study demonstrated that administration of a CD200R antagonist blocked MDSC expansion in glioma tumors and reversed CD200/CD200R-mediated immune suppression." (PMID 38137547, 2023). "Immune checkpoint blockade was an important strategy for glioma treatment; several regular checkpoint molecules were included in our study, and it indicated that except for PVRIG, CD200, and VTCN1, immune checkpoints were substantially higher in the high-risk group." (PMID 36281290, 2022).